CLDN3 (claudin 3)
Diseases named in the same sentence as CLDN3 in open-access papers (continued):
Sharing a sentence is not in itself a finding about the gene and the disease.
ovarian carcinoma (continued). "Although the role of CLDN3 in carcinogenesis is unclear and controversial, high expression of CLDN3 has been reported in various carcinomas including breast, colorectal, gastric, pancreatic, prostate, and ovarian cancer." (PMID 31905631, 2019). "Phosphorylation is shown to be having a regulatory role in the function of claudin-3 and claudin-4, for example, activated PKA or PKC phosphorylates claudin-3 and claudin-4 and enhance the paracellular permeability in ovarian cancer cells through the mislocalization of claudins." (PMID 30728783, 2018). "Finally one more study has demonstrated that the gene expression of CLDN-3, -4, and -6 was significantly lower in malignant peritoneal mesothelioma as compared to ovarian carcinomas." (PMID 28377727, 2017). "Similarly, the upregulation of CLDN3 in ovarian epithelial cancer enhances matrix metalloproteinase-2 activity and is associated with tumor invasion and angiogenic effects." (PMID 28160565, 2017). "Furthermore, other target treatments for CLDN3, siRNA therapy or recombinant shRNA plasmid and cisplatin, have been shown to inhibit ovarian cancer progression and reduce the amount of cytotoxic drugs." (PMID 28160565, 2017). "Claudin-3 and claudin-4 overexpression in this study was determined by their non-detectable expression in normal ovarian surface epithelium based on the notion that ovarian cancer originates in the normal ovarian surface epithelium." (PMID 24009024, 2013). "It is important to note that the upregulation of claudin-3 and claudin-4 expression in ovarian cancer is based on the hypothesis that ovarian cancer arises from normal ovarian surface epithelium." (PMID 24009024, 2013). "Therefore, the overexpression of claudin-3 or claudin-4 has been shown to promote the progression of ovarian cancer." (PMID 24009024, 2013). "Claudin-3 and claudin-4 are highly overexpressed in ovarian cancer including serous carcinoma compared to normal ovarian tissues, and their expression is also upregulated in several other malignancies, including breast, gastric, pancreatic, prostate and uterine cancers." (PMID 24009024, 2013). "Overexpression of claudin-3 and -4 has been shown in ovarian carcinoma." (PMID 24325792, 2013). "Interestingly, phosphorylation of claudin-3 and claudin-4 in ovarian cancer cells has been shown to disrupt tight junctions." (PMID 24325792, 2013). "In particular, overexpression of claudin-3 or claudin-4 in ovarian cancer is based on the hypothesis that ovarian cancers originate from normal ovarian surface epithelial cells, which do not express claudin-3 or claudin-4." (PMID 24009024, 2013). "However, these recent studies indicating the tumor suppressive role of claudin-3 or -4 in ovarian cancer cells are based on results obtained in only one or two cell lines." (PMID 24009024, 2013). "Therefore, further comprehensive studies are necessary to elucidate the exact role of claudin-3 and claudin-4 in ovarian cancer." (PMID 24009024, 2013). "One specific member of this family, claudin-3, has been shown to be overexpressed in multiple forms of cancer, having been most thoroughly studied in ovarian cancer, where it has been shown to be up regulated more than 80-fold in comparison to normal ovarian cells." (PMID 21255442, 2011). "We previously reported in vitro characterization of a fusion protein, CPE290-319-TNF, and demonstrated that the C-terminal 30 amino acids (amino acids 290-319) of CPE could effectively target TNF to ovarian cancer cells expressing claudin-3 and claudin-4." (PMID 21303546, 2011). "The 2008 ovarian cancer cell line expresses both CLDN3 and CLDN4, and we have previously reported on the subline 2008-CLDN3KD-4.5, in which the expression of CLDN3 was knocked down using a lentiviral vector expressing a short hairpin RNA targeted to CLDN3 mRNA." (PMID 21303546, 2011).
ovarian carcinoma (continued). "On the other hand, Claudin-3 and -4 are frequently elevated in various cancers including pancreatic ductal adenocarcinoma, prostate, uterine, ovarian cancer and breast cancer while hepatocellular and renal carcinomas expressed lower levels of claudins-4 and -5." (PMID 20671913, 2010). "On the basis of the high expression of claudin-3 and/or claudin-4 detected by RT-PCR in primary ovarian cancer cell lines we predicted that the FITC-conjugated CPE peptide may bind to ovarian tumors in vitro." (PMID 20598131, 2010). "We next evaluated by confocal microscopy whether the FITC-conjugated CPE peptide is able to internalize after binding to claudin-3 and claudin-4 receptors on the surface of chemotherapy-resistant ovarian cancer cells." (PMID 20598131, 2010). "Similarly to claudin-3, claudin-4 is highly elevated in ovarian cancer." (PMID 32197343, 2020). "Interestingly, in addition to claudin-3 and claudin-4, claudin-6 might serve as a novel receptor for Clostridium perfinges enterotoxin in ovarian cancer." (PMID 32197343, 2020). "However, the associations are not always linear, like in case of claudin-3 or claudin-4 in ovarian cancer, where its expression is increasing during metastases." (PMID 32197343, 2020). "Therefore, CPE-based treatment for malignancies increased CLDN3 expression, such as ovarian tumor, chemotherapy-resistant ovarian cancer and other aggressive solid tumors may be effective." (PMID 28160565, 2017). "This provides proof-of-concept that CLDN3 and CLDN4 are not only markers of ovarian cancer, but also potential therapeutic targets for refractory disease." (PMID 40687428, 2025). "We found that EpCAM and CLDN3 have a pronounced co-expression in various tumor cells, such as OVCAR-3 ovarian cancer cells and NCI-H1781 lung cancer cells." (PMID 40057807, 2025). "CLDN3 and CLDN4 also regulate cisplatin sensitivity in ovarian cancer cells via copper transporter (CTR1), while CLDN7 enhances cisplatin sensitivity in lung cancer cells via the caspase pathway." (PMID 38731853, 2024). "Therefore, CLDN3 may be involved in regulation of the EMT to promote metastasis in ovarian cancer." (PMID 35747825, 2022). "Clinical trials are required to validate the promising results of the in vitro and in vivo studies for CLDN3 and CLDN4, possibly adding onto current ovarian cancer management." (PMID 35665865, 2022). "Eight genes were overexpressed in ovarian cancer samples compared with normal tissue samples and included CLDN1, CLDN3, CLDN4, CLDN6, CLDN7, CLDN9, CLDN10, and CLDN16." (PMID 34249076, 2021). "CLDN3 and CLDN4 is overexpressed in ovarian cancer and increases cell invasion and motility, thereby promoting tumor occurrence and metastasis (Agarwal, D'Souza, and Morin 2005)." (PMID 34721537, 2021). "Among them, CLDN3, CLDN4, CLDN6, CLDN10, CLDN15, and CLDN16 were significantly correlated with overall survival in patients with ovarian cancer." (PMID 34249076, 2021). "Claudin-1 promotes EMT in human liver cells, while claudin-3 and claudin-4 promote EMT in ovarian cancer cells, which suggests that the effect of claudins on EMT is tissue-specific." (PMID 30728783, 2018). "Consistent with our data, CLDN3, CLDN4, and CLDN7 have been shown to suppress EMT in ovarian carcinoma cells and lung cancer cells." (PMID 28867761, 2017). "CLDN3 and CLDN4 are highly overexpression in all subtypes of epithelial ovarian cancers, and these regulation enhances angiogenic effects and invasive properties as well as increased matrix metalloproteinase-2 activity." (PMID 28160565, 2017). "The levels of CLDN3 and CLDN4 were frequently elevated in pancreatic adenocarcinoma, ovarian cancer, endometrioid adenocarcinoma, and prostate cancer, while CLDN7 has been found to be decreased in invasive ductal carcinomas of the breast." (PMID 28867761, 2017). "CLDN3 and CLDN4, which are separated by only 60 kb on chromosome 7, are transcribed in opposite directions and highly overexpressed in ovarian cancer." (PMID 24551595, 2014).
ovarian carcinoma (continued). "Taken together, our results suggest that CLDN3 and CLDN4 serve to maintain the expression of E-cadherin which acts as a central modulator of EMT in the ovarian cancer cells via a pathway involving PI3K/Akt and EMT transcription factor Twist." (PMID 23805314, 2013). "For example, phosphorylation of claudin-3 and claudin-4 by PKA or PKC increases paracellular permeability in ovarian cancer cells via mislocalization of claudins." (PMID 24009024, 2013). "The present observations raise the possibility of exploiting CLDN3 and CLDN4 as potential biomarkers for ovarian cancer progression and highlight maintenance of E-cadherin levels as a target for therapeutic intervention." (PMID 23805314, 2013). "Controversially to our observations, a recent study showed that EGF decreased claudin-3 and -4 via MEK/ERK and/or PI3K/Akt signaling pathways in ovarian cancer cell lines." (PMID 24069372, 2013). "Recent work shows that, in addition to the CLDN3 and CLDN4 genes, CLDN7 is frequently elevated in ovarian cancer." (PMID 21789222, 2011). "We used q-RT-PCR assays to get highly sensitive measurements of claudin-3 and claudin-4 CPE receptor expression in normal tissue cells and primary human tumors derived from patients harboring chemotherapy-resistant ovarian carcinomas." (PMID 20598131, 2010). "Claudin-3 and -4 can be phosphorylated in ovarian cancer cells by PKA, a kinase frequently activated in ovarian cancer." (PMID 20671913, 2010). "In a study conducted in ovarian tissue, Hough and coworkers found that expression of CLDN3 and CLDN4 protein was undetectable in normal ovarian cells and highly expressed on the membranes of ovarian carcinoma cells." (PMID 15743508, 2005). "SAGE (serial analysis of gene expression) demonstrated that, of differentially upregulated mRNAs, CLDN3 and CLDN4 were among the six most upregulated in primary ovarian carcinoma cells." (PMID 15743508, 2005). "Thus, CLDN3 and CLDN4 play multifaceted roles in ovarian cancer, sustaining an epithelial phenotype and promoting survival, invasion, and therapy resistance." (PMID 40687428, 2025). "In ovarian cancer, ZDHHC16 was the dominant enzyme for palmitoylation by claudin 3 (CLDN3)." (PMID 38532349, 2024). "However, CLDN3, CLDN4 40, and CLDN7 41 have been shown to suppress EMT in ovarian carcinoma cells and lung cancer cells." (PMID 34405008, 2021). "CLDN3 and CLDN4, which are Clostridium perfringens enterotoxin (CPE) receptors, affected chemoresistance mediated by CPE in ovarian cancers, it was also reported that CLDN3 and CLDN4 modulated the sensitivity to cisplatin partially through the copper and cisplatin influx transporter CTR1." (PMID 29116019, 2017). "Whereas, the transcriptional activity of CLDN3 and CLDN4 is increased in ovarian cancer." (PMID 29221203, 2017). "As one of the most successful treatment in ovarian cancer, CLDN3 is overexpressed in a majority of ovarian cancer but not detected in normal tissues." (PMID 28160565, 2017). "A recent study also demonstrated that both CLDN3 and CLDN4 regulated EMT in ovarian cancer cells." (PMID 25277196, 2014). "CTR1 gene expression was reduced in CLDN3 or CLDN4 knockdown cells, and enforced CTR1 expression restored their sensitivity to cisplatin, indicating that CTR1 plays a role in cisplatin sensitivity in ovarian cancer cells." (PMID 24009024, 2013). "In fact, CLDN3 and CLDN4 are among the most highly up-regulated genes found in ovarian cancers." (PMID 23805314, 2013). "Because claudin-3 and claudin-4 have been recognized as the receptors for Clostridium perfringens enterotoxin (CPE), these findings imply that ovarian cancer refractory to standard treatment modalities may be susceptible to CPE-based therapeutic approaches." (PMID 20598131, 2010). "Significantly, unlike CA125, claudin-4 and claudin-3 have been shown elevated in all subtypes of ovarian cancer." (PMID 19619303, 2009).
ovarian carcinoma (continued). "Claudin-3 was therefore considered less likely than claudin-4 to represent a useful plasma-based ovarian cancer biomarker and was not studied further." (PMID 19619303, 2009). "Other members of the family, CLDN3 and CLDN4 are frequently overexpressed in ovarian cancer." (PMID 18211683, 2008). "While CLDN9’s functional role in ovarian cancer is not fully elucidated, its presence suggests it might contribute to the malignant phenotype or be exploitable for therapy similarly to CLDN3/4." (PMID 40687428, 2025). "The aberrant expression patterns and the pivotal role of CLDN3 in maintaining cellular polarity and ion flux underscore its significance in cancer pathology and as a candidate for targeted CAR-T cell therapy, aimed at improving treatment specificity and efficacy against ovarian cancer." (PMID 39033780, 2024). "Furthermore, claudin-3 (CLDN3) and claudin-4 (CLDN4) are overexpressed in ovarian cancer." (PMID 35665865, 2022). "While normal ovarian surface cells do not express CLDN3 and CLDN4 these two proteins are up-regulated and expressed at high levels in as many as 92% of ovarian cancers presumably as a result of the MET." (PMID 23805314, 2013). "ZDHHC12 mediates palmitoylation of claudin 3 (CLDN3) at Cys103, Cys106, Cys181, Cys182, and Cys184 to enhance ovarian cancer progression and, reversely, defective CLDN3 palmitoylation inhibits membrane localization and protein stability of CLDN3, with a negative impact on ovarian cancer cell growth." (PMID 36018061, 2023).
breast carcinoma (37 papers, 2005 to 2026). "Some studies have shown correlation between claudin-3 and -4 expression and tumor grade, while other studies have found that certain breast cancer subtypes are associated with different claudin expression levels with different prognostic significance." (PMID 39687048, 2024). "The claudin-low breast cancer (CL-BCa) was identified as one of novel BCa subtypes, and its hallmark was the low expression level of critical cell adhesion molecules, including claudin 3&4&7, Occludin and E-cadherin." (PMID 35359417, 2022). "The observations that high mRNA expression levels of CLDN3 are associated with high tumor grade in our study support that high CLDN3 expression is associated with poor prognosis of breast cancer." (PMID 34531452, 2021). "Conversely, positive claudin-4 expression was associated with shorter disease-free survival and claudin-3 was related to longer disease-free survival in luminal types of breast cancer." (PMID 24009024, 2013). "Low expression of Claudin-3, Claudin-4, and Claudin-7 (CLDN3, CLDN4, and CLDN7) is associated with 3 types of epithelial cancers: breast cancer (BRCA), STAD, and bladder cancer (BLCA)." (PMID 41082105, 2026). "CLDN3, 4, and 6 were also shown as potent regulators of chemoresistance in various malignancies, including ovarian, lung, and breast cancer." (PMID 40943068, 2025). "The level of CLDN3 staining was unrelated to parameters of tumor aggressiveness in pancreatic, gastric, and breast cancer." (PMID 39658782, 2024). "A subset of breast carcinomas show claudin “low” expression profile (as defined by decreased gene-expression of claudins-1, -3, -4, -7, and -8, or by decreased expression of claudin-3, -4, -7, E-cadherin and calcium-dependent cell-cell adhesion glycoprotein)." (PMID 39687048, 2024). "The level of CLDN3 immunostaining was unrelated to parameters of tumor aggressiveness in ductal adenocarcinoma of the pancreas, gastric cancer and breast cancer." (PMID 39658782, 2024). "The binding of CPE to claudin-3 and -4 was documented to induce dose-dependent cytolysis in breast cancer cells expressing claudin-3 and -4." (PMID 31861759, 2019). "Claudin-low breast cancer is a relatively rare breast cancer subtype where the tumor cells possess mesenchymal characteristics as well as very low levels of claudin-3 (Cldn3), Cldn4 and Cdln7; properties that were observed in the RSTs." (PMID 28423599, 2017). "In aggressive breast cancer, expression of claudin-3 and -4 have been shown to be upregulated, while claudin-1 and -7 proteins were downregulated, suggesting that individual claudin family members play different roles in breast carcinogenesis." (PMID 25871476, 2015). "Previous studies have shown that aggressive breast cancer is characterized by upregulation of claudin-3 and -4 and downregulation of claudin-1 and -7 proteins." (PMID 25871476, 2015). "In some studies claudin-3 and -4 are overexpressed in breast cancer and in contrast, claudin-1 and claudin-7 are down regulated, or, completely absent." (PMID 26083392, 2015). "Recently, a new claudin-low molecular subtype of breast cancer was identified that is characterized by low expression of tight junction and adherens proteins, including claudin-3, -4 and -7, and E-cadherin (CDH1), and enriched in stem-like and EMT features." (PMID 24009024, 2013). "The claudin-low subtype is a recently identified molecular subtype of human breast cancer characterized by low expression of tight junction and adherens genes including CLDN3, CLDN4, CLDN7 and CDH1." (PMID 24009024, 2013). "In the present study, CLDN3 appeared to be expressed in a similar manner in primary breast cancers as in normal epithelium." (PMID 15743508, 2005). "Although CLDN3 expression could be found in a wide range of tumor entities, it showed that CLDN3 positivity was most seen in neuroendocrine neoplasms and adenocarcinomas, as well as in tumors of the female genital tract and various subtypes of breast cancer." (PMID 39658782, 2024).